GDF11 (growth differentiation factor 11)
Diseases named in the same sentence as GDF11 in open-access papers (continued):
Sharing a sentence is not in itself a finding about the gene and the disease.
type 1 diabetic (1 paper, 2020). "The present study demonstrated that exogenous GDF11 provides cardioprotective effects against MIR in STZ-induced type 1 diabetic rats." (PMID 31939595, 2020). "Taken together, the findings of our present study provide compelling evidence that exogenous recombinant GDF11 contributes to morphologic and functional recovery after myocardial IR injury in STZ-induced type 1 diabetic rats." (PMID 31939595, 2020). "After treatment with GDF11, those 3 indicators were remarkably decreased, which reflected that GDF11 could reduce myocardial IR injury in STZ-induced type I diabetic rats." (PMID 31939595, 2020).
uremia (1 paper, 2016). A clinical syndrome associated with the retention of renal waste products or uremic toxins in the blood. "Our present study suggests that kinetics and regulation of circulating GDF11 may differ between normal physiological aging process and accelerated pathological aging conditions, such as uremia." (PMID 27298756, 2016). "Since aging process is accelerated in uremia, we compared serum levels of GDF11 in hemodialysis (HD) patients with those in age-matched healthy controls, and then determined the independent clinical correlates of GDF11 in HD subjects." (PMID 27298756, 2016). "Thus, a further study will be needed to address whether supplementation of GDF11 could be functionally correlated with uremia-related organ dysfunction." (PMID 27298756, 2016).
vitiligo (1 paper, 2023). Generalized well circumscribed patches of leukoderma that are generally distributed over symmetric body locations and is due to autoimmune destruction of melanocytes. "This SNP is associated with vitiligo, a skin disease, and GDF11 is known to be involved in the regulation of skin biology." (PMID 37428809, 2023).
cancer (28 papers, 2016 to 2025). A tumor composed of atypical neoplastic, often pleomorphic cells that invade other tissues. "Results from this study indicated that GDF11 caused impairment of cancer cell lipid and glucose metabolism and induced defects in mitochondrial functions." (PMID 38494851, 2024). "Aberrant expressions of GDF-11 are associated with the pathogenesis of cardiovascular, neurological, skeletal muscle, and age-related diseases as well as the risk of cancers." (PMID 35705978, 2022). "Increasing evidence has demonstrated that GDF-11 regulates the development of various organs and its aberrant expressions are associated with the risk of cardiovascular diseases and cancers." (PMID 35705978, 2022). "Cancer-associated changes in the circulating levels of activin family ligands, including activin A, activin B, myostatin and GDF-11, are known to exert effects on muscle and bone homeostasis, thus contributing to the development of overt cachexia." (PMID 29089584, 2017). "However, despite a growing body of research on the role of GDF15 and GDF11 in skeletal and cardiac muscle loss in cancer cachexia, the underlying mechanisms by which these growth differentiation factors facilitate muscle loss remain unknown." (PMID 40558549, 2025). "Like other TGF-β family proteins, GDF11 is pro-angiogenic and it might support muscle regeneration through increased blood vessel formation, albeit at risk of promoting oncogenesis, as GDF11 has a high association with human cancers." (PMID 32033591, 2020). "This work presents an alternative approach to implementing pre-clinical studies that advance and consider the lessons learned from GDF11 as a negative regulator of FOXP3 in this type of cancer." (PMID 40746879, 2025). "As previously reported, GDF11 has biological effects on cancer cells during prolonged incubation, particularly at 72 h; we treated cells for 24, 48, and 72 h." (PMID 40746879, 2025). "Previous works show that GDF11 exerts antitumoral effects in cancer cells, mainly targeting the aberrant metabolism of lipids and bioenergetics." (PMID 40746879, 2025). "GDF11 has been shown to exhibit powerful physiological functions; however, controversy exists regarding its role in cancer biology." (PMID 38611614, 2024). "Previous studies discovered tumour suppressive roles of GDF11 in HCC by reducing HCC cell proliferation, clonogenic capacity, cellular function, and aggressiveness, as well as causing dysregulation of cancer cell metabolism." (PMID 38494851, 2024). "We showed that this basal GDF15 expression gets significantly reduced upon BET inhibition using BI 894999 in a subset of tested cancer cell lines, in which concomitant upregulation of GDF11 was observed." (PMID 37495707, 2023). "As a member of TGF‐β superfamily, GDF11 not only contributes to embryonic development and histogenesis but also plays a role in metabolic disorders, cancers, and heart‐ and skeletal‐muscle rejuvenation in aged mice." (PMID 32515551, 2020). "Overview of cancer cell lines or tissue from patients with differential effect of GDF11, as tumor suppressive or tumor promotion protein." (PMID 31681577, 2019). "This work is focused to review the general knowledge of GDF11, and its functions in cancer biology and metabolism, taking into consideration recent findings in the specialized literature and in the public databases and scientific on-line resources." (PMID 31681577, 2019). "In fact, it is reported that GDF11 impairs mitochondrial function in cancer cell lines, particularly in HCC-derived cells." (PMID 31681577, 2019). "This review is focused to present and analyze the recent findings in the emerging research field of GDF11 function in cancer and metabolism, and discusses the controversies surrounding the biology of this atypical growth factor." (PMID 31681577, 2019).
cancer (continued). "The findings raised by the group of doctors, Wagers and Lee, position cancer cells as a target of GDF11 since they proved that stemness is a key condition for GDF11 effect." (PMID 31681577, 2019). "If GDF11 targets cells with stemness capacity, then many cancer cells should be targeted by this growth factor." (PMID 31681577, 2019). "There exist some controversies in cancer biology as well; in some cases GDF11 induces clear tumor suppressive properties, and in others it is the opposite." (PMID 31681577, 2019). "Many reports have pointed out the effects of GDF11 on cancer." (PMID 40746879, 2025). "Considering these issues, exploring the effects of GDF11 in cancer biology could yield more insights." (PMID 40746879, 2025). "On the other hand, GDF11 may influence the stemness capacity of some cancer cells thereby increasing their aggressiveness." (PMID 38494851, 2024). "In addition to cytokines, other tumor-derived factors are implicated in cancer cachexia such as hormones, metal ions, microRNAs, and members of the TGF-β superfamily including TGF-ß, activin A, growth differentiation factor-11 (GDF-11), and myostatin." (PMID 35994202, 2022). "In addition, proteins of the TGFβ superfamily, GDF3 and GDF11, known to modulate apoptosis in cancer, were also found in the BMSC-EVs." (PMID 36497151, 2022). "In addition, the inhibition of myostatin alone or myostatin and GDF11 by neutralizing antibodies has attenuated cancer cachexia in vivo and muscle atrophy in vitro." (PMID 32365803, 2020). "In the context of the educated guess that cells with some stemness phenotype respond to GDF11, even in cancer, it has been proven that GDF11 negatively regulates NGN3+ progenitor cells and GDF11 induces β-cell differentiation, supporting the role of GDF11 in metabolism." (PMID 31681577, 2019). "Although some studies reported that GDF11 might be a tumor suppressor in some other cancers, such as TNBC, the contradictory results might be a result of the dual role of TGF-β in the different stages of cancer." (PMID 30883611, 2019). "An emerging field of research is the impact of GDF11 in cancer biology." (PMID 31681577, 2019). "GDF11 displays a versatile response that must be fully characterized, due to it representing an interesting point of intervention in many diseases or physiological conditions, particularly in cancer." (PMID 31681577, 2019). "A blunt fact regarding GDF11 biology is that its target cells have stemness feature, a property that could be found in certain adult cells in health and in disease, such as cancer cells." (PMID 31681577, 2019). "It is interesting that, under normal conditions, liver cells, which are the poorest in GDF11 production, are highly responsive to GDF11 in the context of cancer could be relevant in terms of a possible use of GDF11 for treatment." (PMID 31681577, 2019). "Therefore, it can be concluded that the role of GDF11 in different types of cancer is different." (PMID 38143761, 2023). "Furthermore, lung cancer is the most common cancer, and only two studies have shown whether GDF11 exerts a therapeutic effect on it." (PMID 38143761, 2023). "Interestingly, GDF11 has been suggested to be expressed by human cancers." (PMID 28270449, 2017). "In this research, we focused on characterizing the effects of GDF11 on the expression of FOXP3 and its implication in cancer cell aggressiveness." (PMID 40746879, 2025). "GDF11 belongs to the TGF-β protein family, members of which, along with their receptors, are known to play significant roles in regulating cancer." (PMID 38611614, 2024). "Of note, our upstream analysis identified several TGF-beta superfamily of proteins such as MSTN, GDF11, GDF15, TGF-β suggesting their important roles in cancer and in cachexia, offering a window for therapeutic interventions." (PMID 33334063, 2020).
cancer (continued). "Moreover, GDF11 significantly reduces cholesterol and triglycerides in HCC cells and inhibits mTOR signaling pathway, resulting in a defective metabolism of cancer cells." (PMID 38833109, 2024). "Growth differentiation factor 11 (GDF11), also known as bone morphogenetic protein 11 (BMP11), has been identified as a key player in various biological processes, including embryonic development, aging, metabolic disorders and cancers." (PMID 38494851, 2024). "As is the case in aging, and cancer, our data also implicate that skeletal muscle wasting in PAH may also be a phenotype driven by GDF11." (PMID 35524286, 2022). "Growth differentiation factor 11 (GDF-11) pertains to the transforming growth factor β (TGF-β) superfamily, members of which impact numerous processes, such as histogenesis, embryonic development, cancer, and metabolic disorders." (PMID 34712387, 2021). "However, blocking tumor-derived cytokines (“tumorkines”), such as activin receptor (ACVR2) ligands (e.g., activins, myostatin and GDF11), by ACVR2 antagonism has attenuated muscle atrophy and improved survival in experimental cancer." (PMID 32365803, 2020). "This work clearly demonstrates that GDF11 targets hepatic cells with stemness features, not necessarily those observed in cancer, but in the normal liver, particularly in development." (PMID 31681577, 2019). "It seems that mutations in the Gdf11 gene are not the main consequence in those cancers where GDF11 is a prognostic factor, which increases research interest in transcriptional and post-translational regulation." (PMID 31681577, 2019). "However, GDF11 has not been investigated in other cancers and further indepth studies are needed to clarify the mechanism and function of GDF11 in cancers." (PMID 29113418, 2017). "Growth differentiation factor 11 (GDF11) was shown to increase lipid accumulation and DNL in cancer cells, but not in healthy hepatocytes." (PMID 38833109, 2024). "Our results indicate that GDF11 maintains telomere length in Neuro 2a cells, unlike TGF-β which shortens telomere in cancer cells." (PMID 34588995, 2021). "To confirm whether this negative correlation between GDF15 and GDF11 is the result of target-specific inhibition of BRD4 or due to a non-specific effect of the drug on other targets, we looked up literature for gene expression profiling after BRD4 gene knockdown in cancer cell lines." (PMID 37495707, 2023).
tumor (23 papers, 2017 to 2025). "Spearman correlation analysis revealed associations between GDF11 expression and various clinicopathological characteristics, including tumor size, stage, Ki67, and molecular subtypes." (PMID 38611614, 2024). "As a result, GDF11 made a cytostatic condition and caused a decrement in epithelial to mesenchymal transition, resulting in decreased tumour aggressiveness and invasion." (PMID 38494851, 2024). "Moreover, GDF11 has been implicated in the pathophysiology of tumor growth, organ development, aging, and the nervous system." (PMID 38611614, 2024). "In addition, anti-GDF11 antibody has been shown to be able to block muscle loss in tumor-bearing mice confirming its endocrine effects." (PMID 35524286, 2022). "Compared with normal tissues, we observed a reduced methylation level of GDF11 in tumor tissues for selected probes." (PMID 40153751, 2025). "Our results demonstrated a lower GDF11 H-score among patients with larger tumor sizes, advanced stages, higher Ki67 levels, HER2-negative, and specific molecular tumor subtypes." (PMID 38611614, 2024). "Spearman correlation analysis showed significant positive correlations between GDF11 H-score with tumor size < 2 cm, pathologic T0 + T1 + T2 stages, and AJCC 0–II stages." (PMID 38611614, 2024). "The second key finding of this study is the lower GDF11 H-score in the patients with tumor sizes ≥ 2 cm, pathologic stages T3 + T4, and AJCC stages III–IV, which aligns with the findings of a previous study." (PMID 38611614, 2024). "Second, the GDF11 H-scores were lower in the patients with a tumor size ≥ 2 cm, pathologic T3 + T4 stages, AJCC III–IV stages, Ki67 ≥ 14% status, HER2-negative, and the luminal B HER2-negative and triple-negative molecular tumor subtypes." (PMID 38611614, 2024). "Whereas GDF11 reduced HCC cell apoptosis and served them with lipid energy GDF11 reduced tumour progression by inhibiting cell proliferation." (PMID 38494851, 2024). "Third, we identified a significant positive correlation between GDF11 H-score and tumor size < 2 cm, pathologic T0 + T1 + T2 stages, and AJCC 0–II stages." (PMID 38611614, 2024). "Furthermore, because Ki-67 and molecular subtypes may have a confounding effect, we employed multiple linear regression analysis to assess the association between GDF11 H-score and the molecular tumor subtypes luminal B HER2-negative and triple-negative, adjusting for Ki-67." (PMID 38611614, 2024). "We also found a lower GDF11 H-score in the patients with the triple-negative molecular tumor subtype." (PMID 38611614, 2024). "GDF11 is a tumor suppressor, Class II genes are mainly tumor suppressor, including GDF11, TRPV1 and HIC1." (PMID 36741321, 2023). "Previous research has demonstrated that GDF11 has a therapeutic effect on various diseases, such as anti-myocardial aging and anti-tumor." (PMID 38143761, 2023). "Results showed that GDF11 expression was significantly higher in tumor tissues compared with that in adjacent normal tissues." (PMID 30883611, 2019). "CACO-2 cells demonstrated high proliferation in co-culture with CRC-HILEC, but the GDF11 silencing by siRNA abrogated this effect indicating a tumor promotion role of GDF11 in CRC." (PMID 31681577, 2019). "Results showed that GDF11 was generally upregulated in the tumor tissues compared with adjacent normal tissues." (PMID 30883611, 2019). "Since the status of cg05511733 was strongly and negatively correlated with GDF11 expression, we compared the methylation level of this CpG site between the 19 primary tumor and adjacent normal tissues." (PMID 30883611, 2019). "By grouping the tumor cases according to pathological stages, we found that stage IV tumors had the highest GDF11 expression." (PMID 30883611, 2019). "In comparison, GDF11 acts as a tumor suppressor in triple-negative breast cancer (TNBC) via promoting an epithelial and anti-invasive phenotype and also suppresses the proliferation, migration and invasion of pancreatic cancer cells." (PMID 30883611, 2019).
tumor (continued). "Therefore, the tumour suppressive property of GDF11 was concomitant to the decrease in cholesterol transport activity and cholesterol homeostasis." (PMID 38494851, 2024). "The findings revealed a decrease in the H-score of GDF11 in patients with tumor size ≥ 2 cm, pathologic T3 + T4 stages, AJCC III–IV stages, Ki67 ≥ 14% status, HER2-negative, and the molecular tumor subtypes, including luminal B HER2-negative and triple-negative (all p-values < 0.05)." (PMID 38611614, 2024). "However, in vitro studies have shown that the histone deacetylase inhibitor trichostatin A suppresses tumor growth through the activation of GDF11." (PMID 38611614, 2024). "The analysis revealed a persistent significant negative association between GDF11 H-score and the mentioned molecular tumor subtypes (β = −0.491, p = 0.0002)." (PMID 38611614, 2024). "In addition, the GDF11 H-score was lower in the patients with a tumor size ≥ 2 cm, pathologic T3 + T4 stages, AJCC III-IV stages, Ki67 ≥ 14% status, HER2-negative, and specific molecular tumor subtypes." (PMID 38611614, 2024). "The anti‐proliferative role of GDF11 has been demonstrated in tumour cells." (PMID 33764670, 2021). "The impact of GDF11 in the central metabolic organelle could explain the tumor suppressive properties exerted by the growth factor." (PMID 31681577, 2019). "In addition, histone deacetylases (HDACs), a key transcription regulator, also inhibit GDF11 gene expression to regulate the liver development in zebrafish and the growth of tumor cells." (PMID 29113418, 2017). "However, histone deacetylase (HDAC) inhibitor trichostatin A suppressed tumor growth by activating GDF11 in vitro." (PMID 29113418, 2017). "Additionally, cell proliferation of tumour cells was also inhibited by GDF11 in other studies." (PMID 38494851, 2024). "In the tumor-to-tumor signaling direction, activin receptor type-2B (ACVR2B) was implicated in three of the fifteen top-scoring interactions with corresponding ligands of bone morphogenetic protein 5 (BMP5), growth differentiation factor 11 (GDF11), and inhibin beta C chain (INHBC)." (PMID 36676129, 2023). "Additionally, tumor cells expressed Bmp2 and low levels of Gdf11, Bmp4, and Tgfb1." (PMID 38304252, 2023). "GDF15 (P = 1.62E‐12), GDF11 (P = 1.38E‐2), GDF9 (P = 7.2811E‐3), and GDF3 (P = 4.95E‐6) were significantly up-regulated in primary tumor tissue (n = 415) compared with that in normal tissue (n = 34)." (PMID 40153751, 2025). "Tumour aggressiveness, stemness markers, and mesenchymal markers of HCC cells also decreased after GDF11 treatment in Gerardo‐Ramírez's study." (PMID 38494851, 2024). "We found that LHX2, BMP-5 and GDF11 had complex interactions with other missing proteins and BMP-5 had both tumor suppressing and tumorigenic roles." (PMID 32050622, 2020). "Expression of Growth Differentiation Factor 11 (GDF11) was increased in CRC patients and positively correlated with tumor grade." (PMID 31885581, 2019). "The increased expression of GDF11 in primary tumours with no metastasis compared with bone metastasis in BC has been clarified in both cohorts." (PMID 37333824, 2023). "In patients with colorectal cancer, GDF11 was upregulated in tumor tissues compared with adjacent normal tissues." (PMID 30883611, 2019). "Although the protein expressions of PLAU, GDF11, EPS8 and GH1 in tumor and normal groups were not significantly different, the survival analysis results were consistent with our risk model results." (PMID 36741321, 2023).